HLA-B (major histocompatibility complex, class I, B)
Diseases named in the same sentence as HLA-B in open-access papers (continued):
Sharing a sentence is not in itself a finding about the gene and the disease.
spondyloarthritis (continued). "This is a relevant finding given the double implication of HLA-B*27 in the immune-mediated disorders, particularly spondyloarthritis, as well as in viral protection, recently extended to SARS-CoV-2." (PMID 37686141, 2023). "In other diseases of the spondyloarthritis spectrum, the presence of HLA-B*27 is still higher than in the general population, but less than in AS." (PMID 34127053, 2021). "HLA-B*27 allelic genotyping has become important in clinical practice for the treatment and management of spondyloarthropathies." (PMID 33146354, 2020). "After adjustment for HLA-B*27 status, only NKC3 C/C remained linked to spondyloarthritis (adjusted OR = 0.14 (0.06‒0.33))." (PMID 30177859, 2019). "HLA-B*27 presentation of intracellular antigens is thus consistent with HLA-B expression in all spondyloarthritis sites tested." (PMID 29675414, 2018). "The HLA-B*27 allele group, which presents intracellular peptides to CD8+ T cells, is by far the strongest risk factor for spondyloarthritis." (PMID 29675414, 2018). "This study examined the distribution and disease associations of non-HLA-B*27 HLA-B alleles in Romanian spondyloarthritis (SpA) patients, aiming to address the underrepresentation of Eastern European populations in immunogenetic research." (PMID 40806743, 2025). "To contextualize our findings, we examined previously reported associations between non-HLA-B*27 HLA-B alleles and spondyloarthritis across diverse populations." (PMID 40806743, 2025). "The HLA-B27 subtypes that are related to spondyloarthritis (SpA), namely B*27:02, B*27:05, and B*27:07, have a higher propensity to aggregate in cytoplasmic vesicles and form intracellular oligomers compared to the non-SpA-associated subtypes HLA-B*07:02 and HLA-B*27:06." (PMID 40098955, 2025). "This study looked at genetic factors in a group of inflammatory joint diseases called spondyloarthritis, focusing on patients from Northeastern Romania who do not carry a common genetic marker known as HLA-B*27." (PMID 40806743, 2025). "In a large case-control study based in Zambia, López-Larrea and colleagues demonstrated that the presence of the HLA-B*5703 allele was independently associated with both HIV non-progression and the development of spondyloarthropathy." (PMID 34354702, 2021). "HLA-B*27:CAFRW allele frequency was significantly different between the patients with AS and PsA (21.6% and 7.0%, respectively) and individuals without spondyloarthropathies (2.8%)." (PMID 33146354, 2020). "The frequency of HLA-B*27 was 44.4%, 15.8%, and 5.5% in individuals with AS, PsA, and no spondyloarthropathy, respectively; the distribution of frequency was as expected for that observed in Brazilians allowing to validate the technique." (PMID 33146354, 2020). "This could indicate that HLA-B*27 may be able to differentiate between Pso patients who do or do not have PsA, which is also considered a part of the spondyloarthritis spectrum." (PMID 34127053, 2021).
autoimmune disease (26 papers, 2007 to 2025). A disorder resulting from loss of function or tissue destruction of an organ or multiple organs, arising from humoral or cellular immune responses of the individual to their own tissue constituents. "HLA-B*27 was one of the first HLA alleles associated with an autoimmune disease, i.e., axial spondyloarthritis (axSpA) and acute anterior uveitis (B27AAU), which cause joint and eye inflammation, respectively." (PMID 39024572, 2024). "HLA-B alleles are associated with outcomes in various pathologies, including autoimmune diseases and malignancies." (PMID 37597015, 2023). "HLA-B*67:01 has been reported as one of the HLA alleles associated with autoimmune diseases such as Takayasu arteritis and relapsing polychondritis (65, –, 68)." (PMID 36326273, 2022). "In our analysis, we also included allele HLA-B*51 (39 patients) for its known correlation with common autoimmune diseases." (PMID 32854442, 2020). "The HLA 8.1 ancestral haplotype, which includes the HLA-B*08:01 allele, has been associated with a number of autoimmune diseases." (PMID 29989547, 2018). "Interestingly, in our previous study on HLA associations in myasthenia gravis, another autoimmune disease, we also identified HLA-B*08, B*44, B*47, and B*57 as risk alleles." (PMID 40806743, 2025). "Lastly, considering that several HLA haplotypes, including HLA-A*11:01, HLA-A*24:02, and HLA-B*08:01, are associated with COVID-induced autoimmune disease, epitopes affecting these alleles must be carefully considered to minimize the risk of autoimmune adverse effects." (PMID 38784379, 2024). "HLA alleles are not only associated with a set of autoimmune disease; the study in Thai children with autism showed that HLA-B*13:02, HLA-B*38:02, HLA-B*44:03, and HLA-B*56:01 alleles were significantly increased in autistic subjects compared with normal subjects." (PMID 35250581, 2022). "As IgAD has been suggested to be associated with risk for these autoimmune disorders and asthma, our observation suggest a potentially shared common genetic regulatory pathway in the cohorts carrying the HLA-B*08:01-DRB1*03:01-DQB1*02:01 risk haplotype." (PMID 34976003, 2021). "Unexpectedly, myasthenic HLA-B*40 carriers had a significantly higher percentage of autoimmune diseases." (PMID 39728756, 2024). "The genes between HLA-B*08 and DRB1*03 in this haplotype are often associated with autoimmune diseases." (PMID 39768617, 2024). "TNF-α genes are situated in the region of HLA class III (250-kb centromeric of the HLA-B and 850-kb telomeric of the class II HLA-DR genes in humans) and were found to be involved in the incidence and progression of some contagious and autoimmune diseases." (PMID 28119492, 2017). "It is suggested that HLA-B molecules have a superior impact on the outcome of several infectious diseases, inflammatory conditions, autoimmune diseases and malignancies compared to HLA-A molecules, for reasons that remain not well understood." (PMID 26375851, 2015). "It is unlikely that KIR3DL1*001 and HLA-B*51 rose to high frequency in Iran to protect specifically from an autoimmune disease, but this combination of HLA and KIR could also protect against specific infectious diseases." (PMID 32300348, 2020). "Moreover, we detected a strong correlation among the IRP rate and germinal expression of HLA-B*35 and DRB1*11, alleles associated to autoimmune diseases." (PMID 32854442, 2020). "The 8.1 ancestral haplotype (AH8.1) include the classical HLA alleles HLA-B*08:01 and HLA-DRB1*03:01, and has been associated with a large number of autoimmune diseases, but the underlying mechanisms for this association are largely unknown." (PMID 26207384, 2015). "The association of HLA-B*52:01 with myositis and myocarditis has not been seen in previous studies of autoimmune diseases, and may be more inclined towards ICI-specific risk signals." (PMID 41357573, 2025).
autoimmune disease (continued). "This strategy was deployed in both the TyU19 and YTS109 products for autoimmune disease, in which healthy donor PBMC were edited to knock out HLA-A, HLA-B and CIITA, which are required for HLA-II expression." (PMID 41463563, 2025). "In contrast, our findings indicate that HLA-B*08:01, HLA-DQB1*02:01, and HLA-DRB1*03:01 have modest protective effects in depression, indicating that these alleles do not harbor shared risk for autoimmune disease and depression." (PMID 31570195, 2020).
malaria (26 papers, 2009 to 2025). Malaria is a serious and sometimes fatal disease caused by a parasite that commonly infects a certain type of mosquito which feeds on humans. "For example, as generations of African humans survived Malaria, some individuals of African ancestry carry HLA alleles that are known to be resistant to Malaria such as HLA-B*53:01 and HLA-C*06:02." (PMID 38560292, 2024). "Enriched in affected African populations, the B*53 variant of HLA-B, a cell surface protein that presents peptide antigens to cytotoxic lymphocytes, confers protection against severe malaria." (PMID 36823144, 2023). "Our results in conjunction with previous data present a paradox regarding the role of HLA-B*53 in susceptibility to parasitemia and protection from severe malaria." (PMID 33815410, 2021). "While the HLA-C*06:02 association is novel, the association of HLA-B*53:01 with a higher risk of parasitemia is notable in light of prior evidence linking this allele to protection from severe malaria." (PMID 33815410, 2021). "One example is HLA-B*53:01, a protective allele against severe malaria, that exhibits a marked increase of frequencies in areas of Sub-Saharan Africa where Plasmodium falciparum is prevalent." (PMID 27233953, 2016). "The current work, on the other hand, provides novel insights, because it powerfully demonstrates, which group of MHC alleles (supertypes of the HLA-B) accumulates under strong malaria pressure." (PMID 25187124, 2014). "Because of the prevalence of malaria in the Ga-Adangbe and previous associations of cerebral malaria with HLA-B*53:01 and KIR, Plasmodium falciparum is a candidate pathogen." (PMID 24204327, 2013). "A panel of gene polymorphisms has been identified that appear to affect malaria susceptibility by modulation of the immune response or by interfering with host–parasite interactions, including HLA-B, HLA-DRB1, TNFα, IFNγ, IL-1α,β, IL-4, IL-10, IL-22, TLR4,1,6,9, ICAM-1, and complement receptor CR1." (PMID 34578468, 2021). "Enrichment for African alleles of the HLA-B locus may have helped the Colombian population to more effectively counter malaria and/or other pathogenic agents." (PMID 26197429, 2015). "Thus, while there may be population-specific variation in the association of HLA-B*53 with protection against severe malaria, this correlation suggests that HLA-B*53 has undergone pathogen-driven selection in sub-Saharan Africa." (PMID 36823144, 2023). "HLA-A and HLA-B Class I alleles showed systematically more positive effects than Class II loci, suggesting that different evolutionary mechanisms may apply to alleles that mediate immunity to malaria during the liver- and blood-stages of infection." (PMID 25187124, 2014). "Mechanistic studies suggested that this association was mediated by enhanced cytotoxicity against liver-stage malaria parasite forms among carriers of HLA-B*5310." (PMID 38182727, 2024). "This is intriguing, as HLA-B*15:03 is prevalent in West Africa and most countries with high endemic malaria in the African region." (PMID 34578468, 2021). "These genes include inflammatory responding genes, such as NFκB and CXCL1, parasite protein receptors, such as BSG and PROCR, and the genes involving protection against malaria, such as HLA-B and HAVCR1." (PMID 26099491, 2015). "Despite the initial results in The Gambia9, subsequent studies of HLA polymorphism in other malaria-endemic human populations did not replicate evidence of the protective association of HLA-B*5342–44." (PMID 36823144, 2023). "Additionally, while it would have been interesting to explore the influence of HLA-KIR ligand pairs (i.e. KIR2DL1/HLA-C*06:02 and KIR3DL1/HLA-B*53:01) on malaria outcomes, the prevalence of both of these inhibitory KIR in our cohort was >98%." (PMID 33815410, 2021). "More prevalent in the African Region and other countries endemic for malaria is the HLA-B*15:03." (PMID 33901167, 2021).
malaria (continued). "The relationship between HLA-B*53:01 and malaria has been the focus of several prior studies, beginning with a widely cited case-control study conducted in the Gambia that found HLA-B*53 to be strongly protective against severe malaria." (PMID 33815410, 2021). "Therefore, the prediction and evaluation of class I HLA-A and HLA-B epitopes was included as part of our umbrella strategy for evaluation of malaria blood stage vaccine targets." (PMID 34305923, 2021). "Intriguingly, a recent analysis of pooled HLA-A, -B, and -DRB1 data from six randomized trials of RTS,S, the leading malaria vaccine candidate, found that HLA-B*53 was associated with a lack of protection in vaccine recipients, as well as lower post-vaccination titers of anti-CSP antibodies." (PMID 33815410, 2021). "Second, other HLA class I genes, for instance HLA-B (e.g., HLA Bw4 and HLA Bw6 allotypes), which may play a role in malaria risk were not looked at." (PMID 33632228, 2021). "None of the HLA-B alleles was found to have any impact on malaria in this population." (PMID 22220719, 2012). "Given that epidemiological findings have in the past implicated individual HLA class I alleles (e.g. HLA-B*53) with differential susceptibility to malaria infection, we also investigated whether certain KIR–HLA compound genotypes are associated with malaria outcomes." (PMID 22220719, 2012). "Instead, HLA‐B*53:01, DPB1*01:01, DRB1*08:06 and DRB1*11:02 likely confer malaria protection in an independent and complementary way." (PMID 40008064, 2025). "Adaptive and innate immune system related genes and pathways are particularly over-represented among ancestry-enriched segments, including genes (HLA-B and MAPK10) that are involved in defense against endemic pathogens such as malaria." (PMID 26197429, 2015). "Recently, MHC alleles encoding for allotypes with functional similarities to those of HLA-B*53 and HLA-B*78 have also been suggested to play a protective role explaining the likely absence of malaria parasites in bonobos." (PMID 32933484, 2020). "TLDEMRHFY: HLA-A*01:01 and NEVVVKEEY:HLA-B*18:01, were able to directly label ex vivo and thereby identify and enumerate malaria antigen-specific CD8+ T cells in two AdCA-immunized HLA-A*01:01+ volunteers and one AdCA-immunized HLA-B*18:01+ volunteer, respectively." (PMID 24168370, 2013). "None of these alleles at HLA-B, -C or -DRB1 were found to exhibit a statistically significant difference in patients with cerebral and uncomplicated malaria." (PMID 21447146, 2011).
psoriatic arthritis (24 papers, 2011 to 2026). Joint inflammation associated with psoriasis. "The HLA-B*38 allele has been associated with post-transplant lymphoproliferative disorder in solid-organ transplant recipients or susceptibility to develop psoriatic arthritis in the Argentine population." (PMID 39125781, 2024). "Today, HLA-B*38 and HLA-B*39 are strongly associated alleles with susceptibility to Psoriatic Arthritis." (PMID 38892265, 2024). "HLA-B*57:03 was associated with undifferentiated Spondylarthritis in Africans, as well as Psoriatic Arthritis in Chinese." (PMID 38892265, 2024). "Although only a small part of the genetic overlap between AS and psoriatic arthritis is known, HLA-B*27 has been identified as a risk factor for both diseases." (PMID 37798369, 2023). "The effect of Glu at HLA-B position 45 confers substantial risk of psoriatic arthritis and explains previously reported associations at HLA-B∗27." (PMID 25087609, 2014). "HLA-B (rs115860766) is strongly associated with psoriatic arthritis and immune-mediated diseases and may influence local immune responses in the retina." (PMID 41465162, 2025). "In 1985, Woodrow and Ilchysyn were among the pioneers to describe the relationship between HLA-B*13 and psoriatic arthritis (p = 4.3 × 10−4)." (PMID 40428751, 2025). "Among these, HLA-B*15, HLA-B*38 and HLA-B*39 are limited to psoriatic arthritis (PsA), while HLA-B*35 and HLA-B*44 are essentially limited to IBD-SpA." (PMID 38066792, 2023). "With regard to the shared genetic background, associations between MHC-I molecules such as increased frequency of HLA-B*08:01 in SSc and PsO, mainly psoriatic arthritis have been reported." (PMID 30995800, 2019). "This applies to both skin psoriasis (HLA-C*06 and HLA-B*57) and psoriatic arthritis (PsA; HLA-B*27 and HLA-B*39)." (PMID 29963046, 2018). "The aim of this retrospective study on a cohort of HLA-B*51-positive patients who were clinically observed for almost 5 years is primarily to evaluate which classification criteria they satisfy among BD, axial (ax) or peripheral (p) SpA, and psoriatic arthritis (PsA)." (PMID 42123313, 2026). "The HLA analysis in psoriatic arthritis showed a low frequency of HLA-C*06 and absence of HLA-B*27, different from the information reported for Caucasian population." (PMID 39836838, 2024). "Independent of HLA-B and HLA-C, the MICA-129Met allele, especially Met/Met homozygosity, had a strong correlation with the two types of cutaneous psoriasis (PsC) and psoriatic arthritis (PsA)." (PMID 38474281, 2024).